PYCR1 (pyrroline-5-carboxylate reductase 1)
Diseases named in the same sentence as PYCR1 in open-access papers (continued):
Sharing a sentence is not in itself a finding about the gene and the disease.
tumor (continued). "Likewise, up-regulation of L-Pro biosynthesis genes (ALDH18A1 and PYCR1) also reveals L-Pro starvation in tumor cells." (PMID 34458276, 2021). "We hypothesized that it might be mediated by PYCR1 because ectopic PYCR1 expression facilitated tumor cell proliferation and migration." (PMID 33461172, 2021). "This suggests that PYCR1 may play a role in maintaining good mitochondrial function to support maximal respiration under stress, thus presumably contributing to tumor cell survival." (PMID 32960509, 2020). "Different mechanisms have been proposed to explain the ability of PYCR1 to support tumor progression, which could suggest a remarkable degree of pleiotropy and tissue specificity." (PMID 33083024, 2020). "Finally, in support of our results thus far, PYCR1 KO MCF7 tumors showed a marked reduction in tumor volume and weight upon treatment with two cytotoxic drugs." (PMID 32960509, 2020). "A comprehensive study comparing the mRNA expression profiles of 1,454 metabolic enzymes across 1,981 tumors covering 19 different tumor types vs. 931 matched normal tissue controls, identify Proline biosynthesis genes (PYCR1 and ALDH18A1) among the most up regulated enzymes." (PMID 32500033, 2020). "KSHV K1 oncoprotein interacts with and activates PYCR1, promoting tumor growth and development." (PMID 32500033, 2020). "PYCR1 levels were significantly upregulated in tumor tissues (P < 0.01)." (PMID 31619254, 2019). "Both our data and TCGA data proved that PYCR1 was over expressed in HCC tumor tissues." (PMID 31619254, 2019). "Furthermore, PYCR1 mRNA levels in 50 pairs of HCC tumor and adjacent normal liver tissues obtained from TCGA database were analyzed." (PMID 31619254, 2019). "The effect of PYCR1 interference on tumor growth was observed by xenograft nude mice assay in vivo." (PMID 31619254, 2019). "This is the first study correlating PYCR1 with tumor invasiveness and clinical outcome." (PMID 28990419, 2019). "Hence, PYCR1 is a potential target for novel chemotherapeutic agent development, not only as a means to inhibit tumor cell growth, but also to sensitize existing cancer cells that express RRM2B to ionizing radiation and other modalities." (PMID 26733354, 2016). "Furthermore, a study has found that Tregs accumulate in samples with high PYCR1 expression, indicating that PYCR1 may promote tumor immune suppression." (PMID 41035074, 2025). "Additionally, genes such as KCNK1, SHMT2, and PYCR1, which influence tumor metastasis and invasion through histone lactylation, may also serve as biomarkers to help track tumor progression." (PMID 40057816, 2025). "Additionally, PYCR1 interference significantly suppressed tumor growth in nude mice." (PMID 35371311, 2022). "Here, we show that PYCR1 and collagen upregulation co-occur in many types of tumours, and anticipate that further work exploring PYCR1 as a therapeutic target to attack both cancer and stromal cells may result in further development of strategies to treat cancer." (PMID 35760868, 2022). "To investigate the role of PYCR1 in the hypoxic regions of tumors, we engineered a cell model in which PYCR1 could be inducibly knocked down, thereby minimizing the effect of PYCR1 on other cell processes during tumor initiation and initial growth." (PMID 35108535, 2022). "Finally, we assessed the roles of FTO and PYCR1 in xenograft tumor growth in vivo." (PMID 33461172, 2021). "Additionally, hsa-miR-150-5p was negatively correlated with PYCR1 levels in NPC tumor tissues." (PMID 34696668, 2021). "Since however, PYCR1 has recently been found to be upregulated in many cancer cells and to have tumour promoting effects both in cancer cells and CAFs, the development of new inhibitors may prove useful in targeting both tumour and stroma, killing two birds with one stone." (PMID 34513697, 2021). "However, simultaneously overexpress PYCR1 promoted FTO-depleted tumor growth." (PMID 33461172, 2021).
tumor (continued). "In vivo, PYCR1 interference could obviously suppress tumor growth in xenograft nude mice." (PMID 31619254, 2019). "It has been reported that PYCR1 was one of the most frequently overexpressed metabolic genes across 1,981 tumor samples spanning 19 cancer types, suggesting that cancer cells might be addicted to high level of PYCR1 to support cell growth and confer resistance to oxidative stress for cell survival." (PMID 26733354, 2016). "The tumor spheroid size increased in Ctrl A549 cells treated with EGF or TLR agonists, whereas spheroid size was significantly reduced in PYCR1-KO A549 cells treated under the same conditions." (PMID 41254241, 2025). "MS-based profiling of tumor tissues identified enzymes involved in proline biosynthesis, namely PYCR1 and ALDH18A1, as markers of tumor relapse and poor OS." (PMID 40790759, 2025). "Pyrroline 5‐carboxylate reductase 1 (PYCR1) is an essential enzyme for proline synthesis that is abundantly expressed and acts as an oncogene in a variety of tumours." (PMID 39422696, 2024). "Three isoforms, PYCR1, PYCR2, and PYCR3, existed and played significant regulatory roles in tumor initiation and progression." (PMID 39125668, 2024). "In both brain and tumor samples, relative mRNA expression of key proline cycle enzymes, that is, POX/PRODH, PYCR1, PYCR2, and PYCR3, were evaluated, along with the expression of genes associated with ECM degradation, i.e., PEPD, MMP-2, and MMP-9." (PMID 38275897, 2024). "Collectively, these data demonstrate that suppression of proline biosynthesis by targeting PYCR1 reverses psychological stress-induced cGMP-PKG signaling and tumor development." (PMID 37845207, 2023). "First, we analyzed the expression levels of MELK, PYCR1, and PML according to the TCGA database, and we showed that the three hub genes were upregulated in ccRCC tumor tissues compared with matched normal tissues." (PMID 37340189, 2023). "Silencing of PYCR1 effectively reverses psychological stress-induced cGMP-PKG activation and tumor growth, and further inhibits epinephrine-induced cancer stemness." (PMID 37845207, 2023). "Then, we demonstrated the overexpression of PYCR1 and MELK in ccRCC and verified this finding by analyzing tumor specimens, and overexpression of these genes indicates a poor prognosis for ccRCC patients." (PMID 37340189, 2023). "Taken together, these findings uncover a PYCR1-cGMP-PKG signaling axis that is critically involved in regulation of psychological stress-mediated CSC maintenance and tumor growth." (PMID 37845207, 2023). "Here we identify that PYCR1-induced proline biosynthesis enhances TNBC stem cell-like properties and tumor growth." (PMID 37845207, 2023). "We need to conduct further experiments to verify the specific biological mechanisms of PYCR1 and MELK as well as the tumor-immune axis in ccRCC." (PMID 37340189, 2023). "Altogether, these data demonstrate that proline mediates PYCR1-induced CSC maintenance and tumor development in TNBC." (PMID 37845207, 2023). "As a result, our data show that PYCR1 in mammary CAFs represents a stromal vulnerability for ECM production and can be targeted to reduce tumour growth and metastasis." (PMID 35760868, 2022). "Stabilized FTO reduced m6A methylation on pyrroline-5-carboxylate reductase 1 (PYCR1) and extended PYCR1 mRNA half-life to promote BLCA cell proliferation and migration in vitro as well as tumor growth in vivo." (PMID 33461172, 2021). "In the future, we will further explore the correlation between hsa-miR-150-5p-PYCR1 and patient survival and its effect on NPC tumor growth in vivo." (PMID 34696668, 2021). "In conclusion, we showed in the current study the abnormal USP18/FTO/PYCR1 signaling network in BLCA tissue, which favors cell proliferation and migration in vitro as well as tumor initiation and progression in vivo." (PMID 33461172, 2021).
tumor (continued). "Examination of the levels of all pathway proteins showed that mitochondrial proline biosynthesis pathway proteins, PYCR1, PYCR2 and ALDH18A1, are higher in tumor samples relative to normal tissue before and after treatment." (PMID 32960509, 2020). "The emerging evidences that increased PYCR1 and ALDH18A1 expression is a poor prognosis factor in different tumor types are robust and convincing, and suggest an increased need of Proline biosynthesis in cancer cells." (PMID 32500033, 2020). "Due to the fact that PYCR1 was up-regulated in PRCC tissues and cells, we evaluated the relationship of PYCR1 and tumor prognosis in PRCC." (PMID 31428683, 2019). "PYCR1 stabilizes EGFR by facilitating its deubiquitination and simultaneously promotes TLR-mediated NF-κB activation, demonstrating its multifaceted role in tumor progression." (PMID 41254241, 2025). "Notably, treatment with the PYCR1 inhibitor, PYCR1-IN-1, suppressed EGFR-driven 3D tumor spheroid formation, further demonstrating the functional relevance of PYCR1 in EGFR signaling." (PMID 41254241, 2025). "Our results showed that PYCR1, INMT, and KIF20A were significantly upregulated in tumor cells." (PMID 41013841, 2025). "Additionally, our study demonstrated that deferasirox, an oral iron chelator, significantly diminishes cell viability and tumor growth in KRAS-mutant PDAC by targeting FTH1-mediated pathways and altering the PYCR1/PRODH expression ratio." (PMID 39294443, 2024). "Several studies have indicated that overexpression of PYCR1 and PYCR2 accelerates tumor growth." (PMID 39125668, 2024). "RAC3 is a tumor-promoting factor that can promote the proliferation, migration, and invasion of BLCA, and may be related to the activation of the PYCR1/JAK/STAT signaling pathway." (PMID 39659999, 2024). "Out of the three studied PYCR isoforms, only PYCR1 turned out to be uniformly upregulated in tumor tissue, which was corroborated by the three assays performed—RT-PCR, Western immunoblot and IHC; minor differences noted in PYCR2 and PYCR3 did not yield statistical significance." (PMID 38275897, 2024). "In addition, immunohistochemistry was performed on tumour tissues from previous animal experiments, confirming the downregulation of IRS1 after the knockdown/inhibition of PYCR1 in vivo." (PMID 39422696, 2024). "Therefore, expression of POX/PRODH, PYCR1, PYCR2, PYCR3, and PEPD was evaluated in both tumor and brain." (PMID 38275897, 2024). "Further IHC and cellular fractionation analysis indicated PYCR1 was constantly localized in the nucleus of tumor cells with a notable level regardless of oxygen condition." (PMID 37777542, 2023). "We next collected 5 pairs of TNBC tumor tissues and adjacent normal tissues to perform Western blot analysis and the results showed that all TNBC tumor tissues displayed higher levels of PYCR1, cGMP-PKG signaling components and stemness-related factors compared with adjacent normal tissues." (PMID 37845207, 2023). "Subsequently, we validated PYCR1 mRNA expression in tissue samples from 40 patients with ESCC, and confirmed that PYCR1 mRNA was significantly higher in the ESCC tissues compared with adjacent non-tumor tissues." (PMID 35731336, 2022). "PYCR1 protein was obviously expressed in the cytoplasm and nucleus of ESCC tissues, while a small amount was expressed in the cytoplasm and nucleus of adjacent non-tumor tissues." (PMID 35731336, 2022). "PYCR1 mRNA expression was found to be significantly higher in tumor tissues than in adjacent nontumor tissues in 106 paired tumor and adjacent tissues sets (P < 0.05)." (PMID 34239351, 2021). "Indeed, the transcription factor c-Myc triggers expression of PYCR1 and ALDH18A1 in activated T lymphocytes, and there is evidence that proline metabolism contributes to the reprogramming of tumor-infiltrating macrophages." (PMID 33083024, 2020).
tumor (continued). "To find out whether PYCR1 was dysregulated in HCC patients, we determined PYCR1 protein expression levels in tumor and adjacent normal liver tissues of HCC patients by IHC." (PMID 31619254, 2019). "However, there was no statistical difference in PYCR1 expression between different tumor sizes (OR = 1.50, 95%CI: 0.89–2.53) and degrees of differentiation (OR = 0.82, 95%CI: 0.54–1.24)." (PMID 36119513, 2022). "An independent study reveal that PYCR1 is induced in HCC tumor tissues compared to adjacent normal liver tissues and, remarkably, that PYCR1 ablation induces apoptosis, decreases cell proliferation, colony formation ability in vitro, and reduces in vivo tumor size." (PMID 32500033, 2020). "Moreover, reduction of PYCR1 played a negative role on cell proliferation, migration and invasion in tumor cells." (PMID 31428683, 2019). "Moreover, samples with high PYCR1 expression exhibited increased PD-1 + CD8 + T cells and reduced tissue-resident memory T (TRM) cells, indicating that PYCR1 might contribute to CD8 + T cell exhaustion and impact tumor immune surveillance and immune memory functions." (PMID 41035074, 2025).
cancer (88 papers, 2012 to 2026). A tumor composed of atypical neoplastic, often pleomorphic cells that invade other tissues. "An analysis of patient datasets revealed that PYCR1 is upregulated in NSCLC tissues, with the enrichment of cancer-associated pathways in PYCR1-upregulated patients." (PMID 41254241, 2025). "Previous research shows that higher PYCR1 expression is associated with a worse prognosis in different cancers, which is in agreement with our result that shows high expression of PYCR1 is significantly associated with poor prognosis of SNSCC." (PMID 39768999, 2024). "A collection of prominent wGII markers was concordantly identified including the mitochondrial proline biosynthetic pathway enzyme PYCR1, associated with cancer cell survival, invasion, and progression across multiple cancer types." (PMID 38703764, 2024). "The cancer stem cell-associated ALDH+ population significantly declined following ablation of PYCR1 in MDA-MB-231 cells." (PMID 37845207, 2023). "PYCR1 had a high expression in various cancers and was associated with cancer volume and metastasis." (PMID 36119513, 2022). "The PYCR1 gene emerged as one of the most consistently overexpressed metabolic genes in human cancers and its expression is associated with unfavorable prognosis in several malignancies." (PMID 35130302, 2022). "PYCR1 encodes an enzyme that catalyzes the last step of proline synthesis, which plays a key role as an oncogene in cancer progression." (PMID 34696668, 2021). "Of note, overexpression of PYCR1 itself in cancer cells from different tumors is associated with increased intracellular ROS levels." (PMID 33083024, 2020). "The PYCR1 gene has also been linked to multiple cellular capabilities arising from metabolic reprogramming in cancer, including clonogenicity, invasiveness, and metastatic seeding." (PMID 33109600, 2020). "PYCR1 overexpression is linked to the development and growth of cancer." (PMID 40487371, 2025). "PYCR1-mediated proline metabolism regulates multiple cancer phenotypes, whereas the mechanism by which PYCR1 underlines cancer stemness has hitherto remained unknown." (PMID 37845207, 2023). "Due to these functions, proline may be associated with the abnormal expression of PYCR1 in cancer cells." (PMID 37340189, 2023). "Finally, the wound healing assay showed that the SK and PYCR1 siRNA association aroused a tremendous lessening in live cancer cells’ wound healing ability than after a single treatment." (PMID 35293266, 2022). "In conclusion, overexpression of PYCR1 was a potential risk for poor prognosis in various cancers, and PYCR1 might serve as a potential cancer therapeutic target." (PMID 36119513, 2022). "However, we are the first to show in any cancer that PYCR1 interference causes a systematic decrease of the PRAS40 pathway, effectively inhibiting cell growth and mRNA translation." (PMID 35105345, 2022). "ALDH18A1 protein levels and PYCR1 mRNA have also been shown as upregulated in cancer-associated fibroblasts (CAFs), and silencing of these enzymes perturbed collagen formation, in particular collagen type I, α1 (COL1A1)—a crucial extracellular matrix (ECM) component." (PMID 34291343, 2021). "Furthermore, upregulation of PYCR1 has been shown to be associated with increased tumorigenic and metastatic potential in several cancer types." (PMID 32960509, 2020). "Since post‐treatment residual cancer is a prognostic factor associated with survival, we used Cox proportional hazard model to determine whether post‐treatment PYCR1 level alone had prognostic value in our proteomics data." (PMID 32960509, 2020). "PYCR1 confers the final step of proline synthesis and is considered a pro-tumorigenic gene commonly overexpressed in cancers." (PMID 38512964, 2024). "In cancer, PYCR1 acts more like an oncogene, regulating proline metabolism in response to survival stress." (PMID 38744811, 2024).